CHD1L (chromodomain helicase DNA binding protein 1 like)
Diseases named in the same sentence as CHD1L in open-access papers (continued):
Sharing a sentence is not in itself a finding about the gene and the disease.
tumor (continued). "Tumor cells with CHD1L knockout display dramatically less aggressive metastatic behavior and are sensitized to PARP inhibitors (PARPi)." (PMID 40442742, 2025). "CHD1L plays a pivotal role in driving tumor progression, metastasis, and MDR through its unique chromatin remodeling activity." (PMID 40072047, 2025). "In line with this, the TCF/LEF transcriptional program, where CHD1L plays a key regulatory role, has been shown to inhibit immune surveillance by excluding T cells from the tumor microenvironment and inducing immune checkpoint gene expression." (PMID 40442742, 2025). "CHD1L remains a compelling oncology target due to its central role in tumor progression, metastasis, cell survival, and MDR." (PMID 40442742, 2025). "In HCC, CHD1L promotes tumor malignant progression and Sorafenib resistance, which is combated by PARP inhibitor olaparib." (PMID 40234378, 2025). "Based on the Ruijin-RCC dataset, Kruskal–Wallis (K–W) test analysis further confirmed that CHD1L expressions correlated positively with advanced clinicopathological stages, tumor grades, T stages, as well as metastatic status." (PMID 37691108, 2023). "A similar pattern was noticed from the results of the SMART app where statistically significant results from all tumors, except CHOL, showed a higher methylation level of CHD1L in normal versus tumor samples." (PMID 37033447, 2023). "As compared to control tumors derived from shCtrl cells, tumors derived from CHD1L-ablated cells showed a lower tumor growth rate." (PMID 37691108, 2023). "For this purpose, we tried to find if there is a correlation between the upregulation of CHD1L in tumor tissue and those promising biomarkers and our analysis revealed a positive correlation between MSI in READ, LUSC, UCEC, and BRCA and CHD1L expression." (PMID 37033447, 2023). "First of all, we tried to find the correlation between CHD1L expression and the infiltration of two types of immune cells with opposing roles against tumor growth." (PMID 37033447, 2023). "In tumors that had not been treated with chemotherapy, where SPOCK1 exerted strong staining, tumor cell nuclei were also positive for CHD1L." (PMID 37046698, 2023). "For this purpose, it was important to study the correlation between elevated CHD1L expression in tumor tissue and the tumor infiltration of different types of immune cells." (PMID 37033447, 2023). "Analysis of CHD1L correlated proteins in the tumor tissue revealed that POLR3C, PRKAB2, SETDB1, GPATCH4, and MSTO1 were the top five ones." (PMID 37033447, 2023). "We performed CHD1L methylation analysis to study the correlation between CHD1L DNA methylation and tumor progression." (PMID 37033447, 2023). "It affects the infiltration of several immune cells where immunosuppressive cells (MDSC) infiltration was positively correlated with CHD1L expression while the infiltration of tumor-fighting cells (NKT cells) was negatively correlated with the same gene." (PMID 37033447, 2023). "For this purpose, we employed the TISDIB webserver where the generated data demonstrated that the expression of CHD1L was positively correlated with the tumor stage of LUAD and THCA (p < 0.01), KIRP and KIRC (p < 0.05)." (PMID 37033447, 2023). "We also implanted these indicated cell lines into the frank of SCID mice, and CHD1L overexpression notably augmented RCC tumor growth in mice." (PMID 37691108, 2023). "Western blot results from some of the paired HCC specimens showed that the expression of nmMYLK was particularly prominent in the tumor specimens with CHD1L overexpression, as compared with the basal level of smMYLK." (PMID 34588420, 2021). "Several studies have found that CHD1L has a strong carcinogenic ability, including promoting tumor cell proliferation, invasion, migration, metastasis and inhibiting tumor cell apoptosis." (PMID 33663617, 2021). "Taken together, these results demonstrated that autophagy is required for HCC tumor cell migration and metastasis induced by CHD1L." (PMID 34654797, 2021).
tumor (continued). "Further exploration demonstrated that the enhanced tumor cell migration and metastasis induced by CHD1L was mediated through ZKSCAN3-induced autophagic degradation of Paxillin." (PMID 34654797, 2021). "As shown in the represented figures, CHD1L overexpression strongly induced metastatic tumor nodule formation in mice liver (5/5), whereas, this effect was impaired by overexpression of ZKSCAN3 (1/5)." (PMID 34654797, 2021). "In summary, we have identified a novel CHD1L/ZKSCAN3/Paxillin autophagic axis in regulating tumor cell migration and metastasis." (PMID 34654797, 2021). "In this present study, we aimed to analyze CHD1L protein expression in tumor tissues and evaluate its prognostic significance for EC." (PMID 29088777, 2017). "Our previous studies showed that increased expression of CHD1L promoted tumor cell migration and metastasis by increasing cell motility and inducing epithelial-mesenchymal transition (EMT) in HCC." (PMID 26360781, 2015). "A series of our further studies demonstrated that CHD1L contributes to HCC cell migration, invasion and metastasis, and is positively associated with tumor progression in HCC patients." (PMID 26360781, 2015). "CHD1L can contribute to tumor cell migration, invasion, and metastasis by increasing cell motility and inducing filopodia formation and EMT via ARHGEF9-mediated Cdc42 activation in HCC." (PMID 26599012, 2015). "In this present study, therefore, the aim was to analyze CHD1L protein expression in tumor tissue and to assess its prognostic significance for NPC." (PMID 25371726, 2014). "Overexpression of CHD1L protein in tumors is considered to be a biomarker of poor prognosis and short tumor-free survival time." (PMID 24359616, 2013). "Functional studies in vitro and in vivo demonstrated that TCTP has tumorigenic abilities, and overexpression of TCTP induced by CHD1L contributed to the mitotic defects in tumor cells." (PMID 24359616, 2013). "Spontaneous tumor formation was found only in old CHD1L-transgenic mice (over 20 months old), implying that the initiation and progression of HCC carcinogenesis caused by abnormal CHD1L expression is a long process." (PMID 19701453, 2009). "Moreover, knockdown of CHD1L dramatically reduces the ability of tumor cells to proliferate, migrate, and invade neighboring tissues, all critical steps in the metastatic process." (PMID 40442742, 2025). "However, a key oncogenic function of CHD1L appears to be its role as a master regulator of tumor cell survival by controlling the DNA damage response (DDR), cell cycle, and proliferation; and inhibiting programmed cell death mechanisms." (PMID 40072047, 2025). "Indeed, CHD1L has been identified as a promoter of tumor cell proliferation through its mediation of DNA synthesis and G1/S transition." (PMID 40442742, 2025). "Notably, CHD1L is a key regulator of tumor survival pathways, including the cell cycle, DNA damage response and repair (DDR), and the inhibition of programmed cell death." (PMID 39684869, 2024). "Additionally, CpG aggregated methylation data revealed that all of the significant results were in favor of CHD1L hypomethylation in the tumor sample versus normal one (except for CHOL)." (PMID 37033447, 2023). "Moreover, the same tumor survival was found to be kept by CHD1L through the suppression of nucleus-to-mitochondria translocation of nur77." (PMID 37033447, 2023). "Analysis of MDSC infiltration, a cell with immunosuppressive roles in tumor, in the panel of TCGA tumors showed that more than half of the studied tumors experienced a positive correlation between CHD1L expression and MDSC infiltration." (PMID 37033447, 2023).
tumor (continued). "Additionally, we investigated the mutation forms, the correlation with several immune cell infiltration, and the potential molecular mechanisms of CHD1L in the tumor tissue." (PMID 37033447, 2023). "Moreover, it was found that CHD1L affects the tumor immune microenvironment by influencing the infiltration level of several immune cells." (PMID 37033447, 2023). "SIRT7 depends on CHD1L to exert its tumor-promoting functions." (PMID 37691108, 2023). "As expected, CHD1L is not only up-regulated in RCC samples versus adjacent normal sections but associated with tumor clinical stages." (PMID 37691108, 2023). "Our data suggested that CHD1L might be targeted to revert the induced SNAI2 expression thus re-sensitize tumor cells that have acquired resistance to Talazoparib." (PMID 35864202, 2022). "In summary, this work characterizes a previously unknown role of CHD1L in preventing LPS-induced tumor cell death through activating hnRNP A2/B1-nmMYLK axis." (PMID 34588420, 2021). "We proved that the CHD1L/ZKSCAN3 axis was important in cell autophagy-induced HCC tumor migration." (PMID 34654797, 2021). "Considering that CHD1L could induce multiple malignant phenotypes of tumor cells including cell growth and metastasis, how cell autophagy was involved in malignant transformation was first investigated." (PMID 34654797, 2021). "In this study, the correlations between CHD1L and nmMYLK and their roles to tumor cells under LPS mimetic inflammatory condition were investigated, and nmMYLK was found to play an important role in CHD1L-promoted tumor cell proliferation and antiapoptotic effects." (PMID 34588420, 2021). "In addition, immunochemistry (IHC) of both LC3B and CHD1L staining were increased in HCC tumor samples compared with the corresponding para-tumor liver tissues." (PMID 34654797, 2021). "CHD1L promotes nmMYLK expression and prevents lipopolysaccharide (LPS) induced tumor cell death." (PMID 34588420, 2021). "All these findings indicated that CHD1L is required for tumor cell autophagy." (PMID 34654797, 2021). "In summary, we have characterized a previously unknown function of CHD1L in regulating tumor migration via ZKSCAN3-mediated autophagy in HCC." (PMID 34654797, 2021). "Our further study proved that autophagy is indispensable for CHD1L-induced tumor cell migration." (PMID 34654797, 2021). "It is documented that CHD1L is deregulation in various neoplastic diseases." (PMID 33663617, 2021). "Finally, expression of BTF3 and CHD1L in tumor-infiltrating immune cells was further analyzed, and both genes showed significant correlation with CD8+ T cells, suggesting their potential role in CD8+ T cell regulation." (PMID 33644029, 2020). "In CRC, CHD1L was reported to promote tumor progression and to predict poor survival." (PMID 33644029, 2020). "Notably, in three of the seven patients that carried the NMD mutations in CHD1L, DPF2 and BRD7, the genes were down-regulated in these tumor tissues while the same genes in the other patients showed significant up-regulation (FDR < 0.05)." (PMID 31429776, 2019). "CHD1L overexpression was associated closely with ascending pN status (P < 0.001), advanced clinical stage (P = 0.001) and tumor distant metastasis (P = 0.001) in ADCs, but not in SCCs." (PMID 26360781, 2015). "CHD1L positive staining was seen primarily in the nuclei within tumor cells, though occasionally yellowish brown granules could be also observed in the cytoplasm." (PMID 25153161, 2014). "It was additionally found that a high expression of CHD1L correlated significantly with an advanced clinical stage, recurrence and the metastasis status of NPC, indicating that an increase in CHD1L expression could promote tumor growth and invasion." (PMID 25371726, 2014). "CHD1L overexpression was significantly correlated with histologic grade and tumor stage." (PMID 24359616, 2013).
tumor (continued). "Functional studies in vitro and in vivo showed that CHD1L contributed to tumor cell migration, invasion, and metastasis by increasing cell motility and inducing filopodia formation and epithelial-mesenchymal transition (EMT) via ARHGEF9-mediated Cdc42 activation." (PMID 24359616, 2013). "In our previous study, we found that CHD1L has strong oncogenic ability including increasing cell proliferation, colony formation in soft agar, and tumor formation in nude mice, and inhibiting tumor cell apoptosis." (PMID 19701453, 2009). "Further, one patient (no.025) revealed a somatic CHD1L mutation in the tumor)." (PMID 39037077, 2024). "Thus, further research may be focused on the molecular mechanism and the development of novel approaches targeting CHD1L for effective tumor management." (PMID 29088777, 2017). "CHD1L directly promotes the expression of TCTP (translationally controlled tumor protein), contributing to tumor cell growth and enhanced survival." (PMID 40442742, 2025). "In mouse models, CHD1L knockdown or PI3K pathway inhibition reduced metastasis, highlighting the role of this axis in tumor progression." (PMID 40442742, 2025). "In this study, we employ pharmacological inhibition of CHD1L as a seminal approach to provide a comprehensive understanding of its biological function in DDR and tumor cell survival and to illuminate the consequences of CHD1L inhibition." (PMID 39201277, 2024). "It was reported that CHD1L enhanced cell motility and induced filopodia generation through ARHGEF9-mediated Cdc42 activation, a process that collectively stimulated tumor cell migration, invasion, and metastasis." (PMID 37033447, 2023). "Hererin, we provided new evidences that CHD1L can specifically bind to the distal promoter region of ZKSCAN3 and negatively regulates its transcription, which further affects HCC tumor cell autophagy." (PMID 34654797, 2021). "CHD1L negatively controlled the transcription of ZKSCAN3 and prevented the inhibitory role of ZKSCAN3 in tumor cell autophagy." (PMID 34654797, 2021). "CHD1L over-expression occurs in 46% to 86% of HCC and was correlated with venous infiltration, microsatellite tumor nodule formation, advanced tumor stage, poor disease-free survival and poor overall survival." (PMID 25153161, 2014). "Hence, increased expression of both BCL9 and CHD1L may have tumor promoting effects." (PMID 23825644, 2013). "Positive expression of CHD1L protein, as well as other clinicopathological variables (FIGO stage and residual tumor) which were significant by univariate analysis, was included in multivariate analysis." (PMID 23020525, 2012). "Increased expression of CHD1L was often observed at the invasive front of HCC tumors and correlated with venous infiltration, microsatellite tumor nodule formation." (PMID 23020525, 2012). "Furthermore, we demonstrate CHD1Li OTI-611 as a promising targeted therapeutic strategy to exploit vulnerabilities in CHD1L-mediated DDR and tumor cell survival." (PMID 39201277, 2024). "As quantified by the tumor growth curve and tumor weight, we confirmed that SIRT7 could accelerate in vivo tumor proliferation, which could be repressed by CHD1L-KD." (PMID 37691108, 2023). "It is noteworthy that there was no tumor from the analyzed panel that witnessed a negative correlation between CHD1L expression and MDSC infiltration." (PMID 37033447, 2023). "Another interesting finding is that not even one tumor in our analyzed list experienced a positive between CHD1L expression and NKT infiltration." (PMID 37033447, 2023). "Overexpression of CHD1L transcriptionally suppressed the expression of autophagy inhibitor ZKSCAN3, and accelerated autophagic degradation of Paxillin, which is crucial for dynamic disassembly of FA of tumor cells." (PMID 34654797, 2021).
tumor (continued). "Four recurrent deleterious variants corresponding to the CHD1L (99.0%), GFM1 (91.7%), MEIS1 (90.6%) and NFX1 (93.8%) genes were found in the majority of the tumor samples in the study cohort, but in none of the normal controls." (PMID 30416686, 2018). "The results showed that the CHD1L protein levels were significantly increased in tumor tissue samples compared with those in the adjacent non-tumor tissue samples." (PMID 25371726, 2014). "Furthermore, our results show that inhibiting CHD1L with OTI-611 can reprogram chemo/targeted therapy-induced G2/M arrest into G1 arrest in a dose-dependent manner, disrupting cell cycle progression and proliferation to kill tumor cells." (PMID 40072047, 2025). "Putting the results of CHD1L expression and both MDSC and NKT infiltration together we can conclude that the upregulation of CHD1L expression could be used as a marker for a poor immune response against a growing tumor." (PMID 37033447, 2023). "Therefore, our data suggested that CHD1L is indispensable for HIF-2α-positive RCC to sustain tumor growth and metastasis, but not the HIF-2αlow/− subtype." (PMID 37691108, 2023). "On the other hand, chemotherapy-treated tumor samples with weak SPOCK1 expression were negative for CHD1L, suggesting that the regulatory mechanism of SPOCK1 may appear at mRNA level." (PMID 37046698, 2023). "Previously we reported CHD1L overexpression is significantly correlated with the metastasis proceeding of EOC, and may also be an accurate predictor of poor prognosis in EOC patients 16, suggesting that CHD1L may participate in tumor metastasis." (PMID 32922205, 2020). "However, CHD1L expression was not related to tumor size, lymph node status, ER/PR status or molecular subtypes." (PMID 25153161, 2014). "Combined, previous research work supported the hypothesis that CHD1L expression was more likely to be correlated with tumor biology rather than tumor burden." (PMID 25153161, 2014). "Moving to MSI analysis, the expression of CHD1L was found to be significantly positively correlated with MSI in READ, LUSC, UCEC, and BRCA while only one tumor, DLBC, demonstrated a significant negative correlation between CHD1L expression and MSI." (PMID 37033447, 2023).
infection (1 paper, 2023). The state of being infected such as from the introduction of a foreign agent such as serum, vaccine, antigenic substance or organism. "Correspondingly, we performed infection assays in WT (CHD1L expressing) and KO Jurkat T cells and in monocytic THP-1 cells exogenously expressing CHD1L." (PMID 37532928, 2023). "This was confirmed by the observation of increased viral Gag release—a by-product of single-round infection and a correlate of infection rate—from CHD1L-depleted cells." (PMID 37532928, 2023). "Infection assays in iPS cell-derived macrophages and other immortalized cell lines showed increased HIV-1 replication in CHD1L-knockdown and CHD1L- knockout cells." (PMID 37532928, 2023). "However, consistent with results from U2OS cells, we observed lower levels of infection and a significant reduction in p24 production in monocytic THP-1 cells overexpressing CHD1L." (PMID 37532928, 2023).
CHD1L also shares sentences with these, for which no sentence is quoted: lung adenocarcinoma (3 papers); nasopharyngeal carcinoma (3); attention deficit-hyperactivity disorder (2); autism spectrum disorder (2); esophageal carcinoma (2); adenocarcinoma (1); Arteriopathy (1); carcinoid (1); cardiovascular diseases (1); CNS lymphomas (1); colon adenocarcinoma (1); congenital hypothyroidism (1); coronary heart disease (1); diabetes (1); folate deficiency (1); glioblastoma multiforme (1); Insulin resistance (1); intrahepatic cholangiocarcinoma (1); malignant peripheral nerve sheath tumor (1); Obesity (1); Patent ductus arteriosus (1); Pulmonary artery stenosis (1); renal agenesis (1); renal cell carcinoma (1); Renal cortical cysts (1); rhabdomyosarcoma (1); Tetralogy of Fallot (1); thyroid (1); type 2 diabetes (1); undifferentiated ovarian carcinoma (1).
A further 3 diseases each share a sentence with CHD1L in 1 paper.